ESR1 (estrogen receptor 1)
Diseases named in the same sentence as ESR1 in open-access papers (continued):
Sharing a sentence is not in itself a finding about the gene and the disease.
tumor (continued). "Our results clearly show an evolutionary change of gene expression detectable in CTCs in the treatment predictive genes ESR1 and HER2 during tumor progression and selection pressure by systemic therapy." (PMID 28489591, 2017). "Estrogen receptor 1 (ESR1), which mediates ULM development and appears to be expressed in ULMS and c-MET cells, acts in tumor dissemination by activating mitogenic signaling pathways." (PMID 29295562, 2017). "In contrast to ESR1, ESR2 is usually described as a tumor suppressor in estrogen-sensitive malignancies." (PMID 28166815, 2017). "ESR1 (ER), PGR (PR), ERBB2 (HER2) gene expression values tended to be homogeneous across different tumor regions, while MKI67 mRNA levels are slightly varying between regions." (PMID 29187174, 2017). "Results further indicated that miR-129 degraded the Estrogen Receptor 1 (ESR1) mRNA through a post-translational manner and contributed to the decline of stem-like cells number, preventing tumor regeneration." (PMID 29262559, 2017). "Statistically significant differences emerged in the distribution of EGFR, CCND1 and ESR1 CNVs according to ER, HER2, MIB1 and tumor size (T) status." (PMID 27765917, 2016). "We revealed TFs whose expression is linked to a large number of tumor-specific enhancers and further characterized selected TFs for each tumor type (e.g., BRCA: GATA3, FOXA1, ESR1, PRAD: HOXC6, DLX1, KIRC: ZNF395) and for specific tumor subgroups." (PMID 27833659, 2016). "Recent studies have suggested the existence of at least two subgroups within tumours with an amplification on the HER2-locus, expressing high or low levels of the ESR1, GATA3 and BCL2 gene cluster." (PMID 27341628, 2016). "DNA methylation of estrogen receptor 1 (ESR1) and progesterone receptor (PR) promoters has been proposed as a mechanism for the development of ER-negative tumours." (PMID 26220712, 2015). "They identified 37 genes (out of 48 examined) with significantly different methylation levels between tumor and normal tissue; 32 genes were hypermethylated and five genes were hypomethylated (BMP6, DIRAS3, ESR1, HRAS, and SFN) in the cancerous tissues." (PMID 26561834, 2015). "The expression of genes in tumours was low for CD3Z, CD8, CXCL13, SNAI2 and ESR1 (40-DCq <32) and moderate for IGHM, CD4, CXCL9 and FOXP3 (40-DCq 32–35)." (PMID 25970543, 2015). "We found substantial changes of both DNA methylation and mRNA expression of CR1, ESR1, PTPN13, and SOCS2 in HCCs compared with paired non-tumor tissues, which is consistent with the results obtained by analyzing the array data in our discovery sample." (PMID 25965583, 2015). "Moreover, our analysis shows ESR1 regulation of genes involved in anatomical structure morphogenesis/tissue remodeling (genes, e.g. coding for collagen and fibronectin) that are progressively downregulated upon PB treatment and remain repressed at the tumor stage." (PMID 24464994, 2014). "Protein and RNA quantitation analyses of primary tumor samples have shown that HER2 and ESR1 expression are anti-correlated in HER2+ tumors, while they tend to be uncorrelated or even positively correlated in HER2- tumors." (PMID 24828673, 2014). "In the case of BRCA1 vs BRCA2 tumours, only four of the influential TFs (GATA3, ESR1, FOXA1 and XBP1) were identified as differentially expressed." (PMID 25521701, 2014).
tumor (continued). "RNase pretreatment resulted in a higher fraction of tumor cells showing point-shaped FISH signals, by eliminating fuzzy clusters (fringes, tails or clouds) of ESR1 FISH probe signals seen in many nuclei by standard FISH." (PMID 24367641, 2013). "Samples that stained positive for ER, PR and HER2 resulted in DASL mRNA average transcript fold changes in ESR1, PGR and ERBB2 (95% CI) of 4.46 (2.01–6.90), 3.41 (1.24–5.58) and 3.59 (1.40–5.77) greater than their respective IHC-negative tumours." (PMID 22067903, 2011). "The identified genes are involved in drug transport and detoxification (ABCB1, DNAJC15, GSTP1, RAB6C), DNA damage repair (BRCA1) as well as tumor cell proliferation/invasion (APC, CDH1, ESR1, HIC, PLAU, RASSF1, SULF2, TGM2)." (PMID 20544021, 2010). "In a study recently published, basal-like tumour cell lines were characterized by the concomitant hypermethylation of a six gene panel (CDH1, CEACAM6, CST6, ESR1, LCN2, SCNN1A)." (PMID 20338046, 2010). "We then investigated the expression of ESR1/ERα and that of the five following top-ranked genes (MET, FOS, SNCG, IGFBP4, and BCL2) by RTQ-PCR on the initial set of 18 tumor samples (eight control and 10 TF)." (PMID 18928543, 2008). "From a mechanistic standpoint, our results suggest that OCs could interact with the pre-existing ESR1 A908G mutant receptor in early pre-neoplastic breast lesions to stimulate epithelial proliferation, thus driving the accumulation of additional genetic errors leading to neoplasia." (PMID 17553133, 2007). "Furthermore, our database contains receptors including ESR1, FGFR2, and VDR, which are recognised for their roles in cellular responses and tumour development." (PMID 40754672, 2025). "Notably, the expression of ESR1, ERBB2, and Ki67 has been investigated for their correlation with tumor stage and grade." (PMID 40948378, 2025). "In contrast, KTC-1 cells (from a male patient whose tumor lacked E2 sensitivity) showed no such response, likely reflecting variations in ESR1 expression, co-regulator availability, or epigenetic modifications." (PMID 41250218, 2025). "Amongst these are notable tumor related genes AKT3, CDKN1A, ESR1, FOXO1, TSC2, ERBB3, and NRG4." (PMID 40522948, 2025). "No estrogen response ARPs were detected in the tumor epithelium despite high ESR1 expression in tumors from older patients, further supporting the model of positive feedback regulation under low postmenopausal estrogen." (PMID 41188599, 2025). "The results of network pharmacology and molecular docking analyses suggested that SSA may interact with BCL2, ESR1, HIF1A, and STAT3 as well as PI3K/AKT signalling pathways and inhibit tumour growth by promoting apoptosis." (PMID 39995416, 2025). "Spatial transcriptomics and scRNA-seq demonstrated the robust expression of estrogen receptor 1 (ESR1) and progesterone receptor (PGR) in fibroids with significant involvement of the ERK1/ERK2 pathway in mediating hormonal effects and promoting tumor progression." (PMID 39936948, 2025). "There were no estrogen response ARPs in the tumor epithelial cells despite the shift toward luminal A and high ESR1 expression observed in the older METABRIC cohort." (PMID 39483921, 2024). "Additionally, it acts as an anti-tumor agent by inhibiting SRC/MAPK/ERK pathways and regulating the expression of ALB, ESR1 and SRC." (PMID 39544939, 2024).
tumor (continued). "CASP3, SRC, ESR1, JAK2, PRKACA, HSPA8 and CAT exhibited stronger interactions with other factors, suggesting that they may be the key targets for tumor treatment." (PMID 38675723, 2024). "Whereas the other, including both women and men patients with high ESR1 expression, is characterized by vascular normalization without the other tumor processes (therefore called non-necroinflamed tumors)." (PMID 38411438, 2024). "Unlike ESR1, estrogen receptor 2 (ESR2) is expressed in CRC and is associated with tumor suppression." (PMID 39327445, 2024). "Additionally, there is a crucial need to investigate the molecular pathology of UTROSCT, specifically the impact of gene fusions such as NCOA, ESR1, and GREB1 on tumor behavior and prognosis." (PMID 38968462, 2024). "Statistical analysis using two-way ANOVA showed that menopausal status and tumor grade do not affect ESR1 expression at the mRNA or protein levels." (PMID 36769338, 2023). "There was no obvious relationship between the survival rate of the tumor patients and the RNA levels of ESR1 and ESR2 (p > 0.05)." (PMID 37762356, 2023). "Moreover, considering tumor heterogeneity and the small size of our population, looking for ESR1 mutations may not be sufficient, since other mutations, such as in the MAPK, PI3K/AKT/mTOR, and CDK4/6 pathways, have been demonstrated to be involved in the mechanisms of resistance." (PMID 36831647, 2023). "In an exploratory analysis, based on tumor biomarkers, the efficacy was better in patients who had no ESR1 mutation (ESR1 wild type); median PFS for the ESR1-WT treated with ribociclib was 8.3 months, compared to 2.7 months for those on placebo." (PMID 37860199, 2023). "In PDX models with and without ESR1 mutations, oral daily administration of ARV-471 resulted in tumor regression." (PMID 37019913, 2023). "ESR1 was also the top enriched TF for the HGSC subtype, suggesting a major role for this TF in regulating aberrant epigenomic landscapes that lead to HGSC tumour development." (PMID 37120667, 2023). "KEGG pathway analysis of tumor RNASeq data showed that the ER signaling pathway was the most impacted pathway in ESR1-Y537S mutant tumors treated with the combination but not with either single agent." (PMID 37568775, 2023). "Estradiol levels were significantly correlated with expression of oestrogen response early (FDR = 0.01, Spearman) and late (FDR = 0.02, Spearman) GSEA Hallmarks but no other hallmarks in tumours with high ESR1 expression." (PMID 37419892, 2023). "However, our data reveal a decreased ESR1 GEX in the LNM, where tumor cells remain naïve to endocrine treatment." (PMID 38449790, 2023). "Together with the fact that we observed a significant correlation between age and ESR1 promoter methylation in WBCs, it is likely that part of the ESR1 methylation signal in cfDNA was not tumor-specific." (PMID 35628441, 2022). "The median expression of ESR1 and HSP90AA1 was significantly increased in tumor cells." (PMID 35273218, 2022). "Overrepresentation of targets for ESR1 and FOXA1 in the luminal subtypes is in line with the cooperation between these two transcription factors and the importance of oestrogen signalling in these tumours." (PMID 35182081, 2022).
tumor (continued). "Meanwhile, the methylation level of ESR1 and CYP3A4 in tumor samples was significantly higher than that in normal samples, implying that methylation could be one of the factors leading to abnormal gene expression." (PMID 35356272, 2022). "ESR1 was downregulated in recurrent tumors in the HER2-positive subgroup, along with decreases in genes coding the phosphatase and tensin homolog, a tumor suppressor and transforming growth factor-β (TGFβ), a multifunctional cytokine." (PMID 35351903, 2022). "Note that CCDC170, but not ESR1, mRNA levels were significantly higher in these normal (adjacent to tumor) tissues than in cancer tissue (Kruskal Wallis Test P < 0.0001." (PMID 35151276, 2022). "Protein–protein interaction of the gene in the ceRNA networks shown that the high-scoring proteins were obtained including CD44, MYC, CCND1, ESR1, IL6, and VEGFA, which suggesting that they might jointly regulate the occurrence and development of tumor." (PMID 34655361, 2021). "Our findings reveal a novel insight that IR-induced ferroptosis was via two-way regulation of ESR1/NEDD4L to SLC7A11, and ESR1 might be a critical factor responsible for conferring the resistance to radiotherapy and tumor malignancy." (PMID 35252218, 2021). "The anticancer effects of AA on HCC were predicted to be associated with regulating tumor cell proliferation, apoptosis, angiogenesis, tumor invasion, and metastasis via various pathways such as the EGFR signaling pathway, ESR1 signaling pathway, and CCND1 signaling pathway." (PMID 33688369, 2021). "We speculate that Shan Ci Gu may play a role in inhibiting tumor cell proliferation by targeting several proteins such as EGFR, SRC, and ESR1 in NSCLC." (PMID 34178945, 2021). "The expression levels of STAT4, ETS1, or ESR1 did not significantly differ between the tumor and control groups." (PMID 35155179, 2021). "From the ginsenoside-target-pathway network, we observed that EGFR, ESR1, ESR2, HSP90AA1, and RELA are all critical genes that we should focus on, which may reveal the anti-tumor mechanism of G-Rk1 and G-Rg5." (PMID 34199025, 2021). "The authors saw a 70% increase in tumor multiplicity in Esr1 KO mice, but this increase was not significant." (PMID 34068249, 2021). "In experiments, breast cancer cells expressing ESR1-MUT versus ESR1-WT require 10- to 50-fold higher doses of fulvestrant to achieve equivalent inhibition of ER transactivation function, cell proliferation, and PDX tumor growth." (PMID 34392831, 2021). "Tumours with high expression of both ERBB2 and ESR1 could be of special interest, since these seem to interact with each other under endocrine therapy, providing a resistance mechanism." (PMID 34073233, 2021). "ESR1-MUT may selectively attenuate the efficacy of the anti-estrogen component of a combination regimen, and subsequent tumor response becomes dependent on sensitivity to the partner agent (CDK4/6i, PI3Ki, or mTORC1i)." (PMID 34392831, 2021). "As the overall expression across all tumours and subtypes revealed differences for KRT20, ERBB2, and ESR1 mRNA expression, the potential predictive value of the target gene expression of KRT20, ERBB2, and ESR1 was further analysed by partitioning test." (PMID 34073233, 2021). "We applied the developed ESR1-NAPA assay to analyze 13 primary tumours from ER-positive breast cancer patients, and from 13 non-cancerous breast tissues (mammoplasties), which were used as the wtDNA control." (PMID 33535614, 2021). "The female Esr1 KO mice in the tumor study, unlike untreated Esr1 KO females, had reduced body weight and approximately twice the liver weight and liver to body weight ratio." (PMID 34068249, 2021). "These hub biomolecules of tumor stroma network, AR, GATA2, miR-124, TOR1AIP1, ESR1, EGFR, STAT1, miR-192, GATA3, COL1A1, may give crucial information about tumorigenesis." (PMID 33907495, 2021).
tumor (continued). "Our studies investigate the importance of Esr1 and Esr2 in HCC development in female mice, and show that Esr1, but not Esr2, is a key mediator of tumor outcome." (PMID 34068249, 2021). "Six tumor types (including BLCA, BRCA, CHOL, LUSC, PCPG, and UCEC) showed significant lower DNA methylation of ESR1 in tumor tissues than healthy tissues and four tumor types (including CESC, COAD, KIRC, and PAAD) significant higher DNA methylation of ESR1 in tumor tissues." (PMID 32536040, 2020). "Relative E2 amount was positively associated with ESR2 (ERβ) mRNA expression (r = 0.61; P = .0358), but not ESR1 (ERα) mRNA expression in women with ER+/PR+ tumor." (PMID 31853538, 2020). "The IHC results suggest that indeed the apparent reduction in ESR1 signaling observed globally was a result of change in microenvironmental composition rather than changes in the tumor cells themselves." (PMID 33203854, 2020). "In one of the tumours DES-ir, ESR1-ir and PGR-ir decreased significantly after 10 days of culture." (PMID 32251338, 2020). "The pathway enrichment analysis result showed that ESR1 and ESR2 correlated genes enriched in some immune response and immune cell activity pathways indicated an essential relationship between estrogen receptor and tumor immunity in many cancer types." (PMID 32536040, 2020). "These analyses also showed an enrichment for hypomethylated binding sites of transcription factors (e.g., ESR1, ESR2, FOXA2) and histone proteins (e.g., H3K4m1, H3K4m2, H3K4m3, H3K27m3, H3K9m3) in GBM2 compared to GBM1, suggesting a role for these factors in tumor progression." (PMID 32779022, 2020). "In the rat breast precancerous lesions model, high and low dose RYNXC could also significantly reduce genes and proteins expression of ESR1, PGR, PTGS2, EGFR, and Src." (PMID 30906412, 2019). "In contrast, a significant negative correlation of CYP19A1 and ESR1 levels was found in tumor cell lines (r = −0.639, P = 0.012)." (PMID 29363090, 2018). "In fact, 81% of ESR1− and 78% of ESR1+ tumours were GREB1+ by IHC, with no major differences across subtypes." (PMID 29973689, 2018). "One study used a different hypermethylated gene panel (RASSF1A, ESR1, CDH1, TIMP3, SYK) in the hopes of finding more concordant data; however, only 17% of patients in that study had simultaneous methylation of a gene in the tumor and in the blood." (PMID 29614786, 2018). "Previous reports have proposed that ESR1 and ESR2 could have a tumor suppressor role in prostate gland." (PMID 29731970, 2018). "Esr1 deletion in tumours prolonged survival and decreased, but did not eliminate, E2 responsiveness." (PMID 29973689, 2018). "Tumor cell content, DCIS content, HER2 immunohistochemical score of the invasive tumor and the DCIS, as well as relative expression of the mRNA markers ERBB2, ESR1, PGR and MKI67 and absolute Δ40-ddCq values are shown." (PMID 30342538, 2018). "In addition, we found a correlation between the methylation levels in tumors and tumor-distant tissues for BRCA1 (r = 0.826, p < 0.001) and ESR1 (r = 0.555, p = 0.017)." (PMID 28403857, 2017). "The Multiple Beam Search (MBS) algorithm learned interactions from data and discovered that hsa-miR-21, hsa-miR-10b, hsa-miR-448, and hsa-miR-96 interact with oncogenes, such as, CCND2, ESR1, MET, NOTCH1, TGFBR2 and TGFB1 that promote tumor metastasis, invasion, and cell proliferation." (PMID 28793339, 2017). "For the following genes, a correlation was found between the methylation levels in tumors and those in tumor-adjacent tissues: CDKN2A (promoter) (r = 0.927, p < 0.001); BRCA1 (r = 0.878, p < 0.001); APC (r = 0.706, p = 0.001), ESR1 (r = 0.545, p = 0.019) and ESR2 (r = 0.543, p = 0.024)." (PMID 28403857, 2017). "To investigate whether the tumours with high immune gene expression (as represented by CD8A expression) show low levels of GATA3, ESR1 and PGR, we scattered each of these proteins against CD8A RNAseq counts." (PMID 26729235, 2016).